C1orf35 (chromosome 1 open reading frame 35)
Synonyms: MMTAG2; MGC4174
Tractability: Antibody: its Gene Ontology location is reachable by antibodies, with high confidence; the Human Protein Atlas places it where antibodies can reach. PROTAC: UniProt records ubiquitination sites on it; ubiquitination databases record sites on it; its protein half-life has been measured.
Gene: Protein-coding gene on chromosome 1 (228,100,725 to 228,105,411, reverse strand). Ensembl gene ENSG00000143793.
Subcellular location (Human Protein Atlas): Nuclear speckles; Plasma membrane; Cytosol
Pathways (Reactome):
Immune System: Neutrophil degranulation
Gene Ontology:
Molecular function: protein binding; RNA binding
Cellular component: extracellular region; ficolin-1-rich granule lumen; secretory granule lumen
Genetic constraint (gnomAD): Loss-of-function variants: 36 observed, 27.51 expected, observed/expected ratio (o/e) 1.31, 90% interval 1 to 1.72. The synonymous counts are far from expectation, so gnomAD's model fits this gene poorly and the ratio says little. Missense variants: 396 observed, 324.29 expected, observed/expected ratio (o/e) 1.22, 90% interval 1.12 to 1.33. Synonymous variants: 179 observed, 125.89 expected, observed/expected ratio (o/e) 1.42, 90% interval 1.26 to 1.61.
Homologues: Orthologues: chimpanzee C1H1orf35 (100% identical), rabbit C1orf35 (83% identical), mouse 2310033P09Rik (80% identical), guinea pig C1orf35 (79% identical), dog C1orf35 (73% identical), pig C1orf35 (71% identical), rat C10h1orf35 (62% identical), tropical clawed frog c6h1orf35 (57% identical), zebrafish C2H1orf35 (52% identical).
Diseases named in the same sentence as C1orf35 in open-access papers:
C1orf35 is named in the same sentence as 8 diseases in open-access papers, as found by Europe PMC text mining. Sharing a sentence is not in itself a finding about the gene and the disease. The quoted sentences say what the papers report.
liver cancer (2 papers, 2021 to 2024). An epithelial or non-epithelial malignant neoplasm that arises from the liver. "Further studies have suggested a potential role for C1orf35 in liver cancer." (PMID 39575189, 2024). "Besides previously reported dysregulated genes, the current study identified new candidate genes with a putative role in liver cancer, e.g. C1orf35, PAFAH1B3, ZNF219 and others." (PMID 33541355, 2021).
colorectal cancer (1 paper, 2026). A primary or metastatic malignant neoplasm that affects the colon or rectum. "The functional significance of Chromosome 1 open reading frame 35 (C1orf35) in colorectal cancer (CRC) remains poorly characterized." (PMID 41930328, 2026).
gastric cancer (1 paper, 2024). A primary or metastatic malignant neoplasm involving the stomach. "Promoter hypomethylation of C1orf35 and FAAH in early-stage gastric cancer underscores their potential as biomarkers for accurate diagnosis and treatment." (PMID 39575189, 2024). "Notably, the hypomethylation of the three CpG islands in C1orf35 and the single CpG island in FAAH was significantly different in stage I/II gastric cancer patients compared to normal tissues." (PMID 39575189, 2024). "Central genes like C1orf35 and FAAH have demonstrated both predictive and prognostic significance as biomarkers based on methylation, setting the stage for accurate diagnosis and targeted treatment of gastric cancer." (PMID 39575189, 2024).
multiple myeloma (1 paper, 2024). "C1orf35, identified in multiple myeloma cell lines, acts as an oncogene promoting the G1-to-S cell cycle transition by modulating c-MYC expression." (PMID 39575189, 2024).
tumor (1 paper, 2026). "Functional assays, including experiments in patient-derived organoids, demonstrate that C1orf35 is essential for driving tumor cell proliferation, migration, and expansion." (PMID 41930328, 2026). "Thus, our work defines C1orf35 as a dual-function oncoprotein that promotes CRC progression by coordinately enhancing tumor-intrinsic growth via the c-Myc/PYCR2 axis and fostering an immune-suppressive niche." (PMID 41930328, 2026). "Through c-Myc, C1orf35 impairs the cytotoxic function of tumor-infiltrating CD8+ T cells." (PMID 41930328, 2026). "We report that C1orf35 is frequently upregulated in CRC clinical specimens, and its elevated expression correlates strongly with advanced tumor stage and serves as an independent prognostic indicator for reduced overall survival." (PMID 41930328, 2026). "Furthermore, we uncover a distinct, non-cell-autonomous function of C1orf35 in shaping the tumor immune microenvironment." (PMID 41930328, 2026).
C1orf35 also shares sentences with these, for which no sentence is quoted: cancer (1 paper); hepatocellular carcinoma (1); preeclampsia (1).